ALDH1A1 (aldehyde dehydrogenase 1 family member A1)
Diseases named in the same sentence as ALDH1A1 in open-access papers (continued):
Sharing a sentence is not in itself a finding about the gene and the disease.
osteoporosis (4 papers, 2013 to 2025). A condition of reduced bone mass, with decreased cortical thickness and a decrease in the number and size of the trabeculae of cancellous bone (but normal chemical composition), resulting in increased fracture incidence. "In the present study, we first demonstrated disulfiram suppressed ethanol-induced osteoporosis either in vitro or in vivo, the deep mechanism contributed to the ALDH1A1-NFATc1 axis." (PMID 31596733, 2019). "Moreover, disulfiram also decreased ethanol-induced osteoporosis in vivo, making ALDH1A1 a potential target for future treatment of ethanol-induced osteoporosis and osteoclast-osteoporosis." (PMID 31596733, 2019). "Combined with the in vitro data, these findings demonstrate that alcohol consumption induced the expression of ALDH1A1, while disulfiram protected against it, and thus targeting ALDH1A1 may be a potential method of therapy for osteoporosis." (PMID 31596733, 2019).
anaplastic thyroid carcinoma (3 papers, 2014 to 2024). "The upregulation of cell surface markers such as CD44, CD133, and ALDH1A1 has been linked to a poorer prognosis and increased resistance to chemotherapy and radiotherapy in both differentiated (DTC) and undifferentiated thyroid carcinomas (UTC)." (PMID 39595993, 2024).
benign prostate hyperplasia (3 papers, 2020 to 2021). "Also, it can be partially attributed to the significant upregulation of aldehyde dehydrogenase 1A1 (ALDH1A1) expression in benign prostate hyperplasia tissues in response to Gln starvation." (PMID 34335968, 2021). "The authors have demonstrated that 6-substituted-imidazo[1,2-a] pyridine derivatives inhibited ALDH1A1 and ALDH1A3 gene expression and the proliferation of cancer cell line PC3, normal prostate epithelial cell line PNT2-C2, and benign prostatic hyperplasia cell line BPH1." (PMID 34572930, 2021).
cataract (3 papers, 2013 to 2023). Partial or complete opacity of the crystalline lens of one or both eyes that decreases visual acuity and eventually results in blindness. "In the same study, ALDH1A1 knockout mice were found developing cataracts at 6–9 months of age especially sensitive to UV light." (PMID 28177569, 2017). "Therefore, the present study focused on quantitative relationships of SOD2, ALDH1A1, and MGST1 messenger ribonucleic acid (mRNA) levels between patients presenting with cataracts with and without PEX." (PMID 23805041, 2013).
cervical squamous cell carcinoma (3 papers, 2015 to 2025). A squamous cell carcinoma arising from the cervical epithelium. "There is not much information about the regulation of ALDH1A1 expression in cervical lesions, but the function of ALDH1A1 in squamous cervical cancer has been described in several studies." (PMID 34830452, 2021). "In TCGA-cervical squamous cell carcinoma (CESC) cohort, CBX2 expression was positively correlated with the expression of the cancer stem cell markers SOX2 and ALDH1A1." (PMID 39793896, 2025).
clear cell renal cell carcinoma (3 papers, 2014 to 2020). "For example, ALDH1A1 showed high expression in clear cell renal cell carcinoma compared with normal tissues." (PMID 24485040, 2014).
fatty liver disease (3 papers, 2021 to 2024). A reversible condition wherein large vacuoles of triglyceride fat accumulate in liver cells via the process of steatosis. "WIN18446 has also been shown to be a potent antiobesity treatment due to its inhibition of ALDH1a1, although hepatic lipidosis is a side effect of the drug that is not witnessed in ALDH1a1 knockout mice or disulfiram-treated mice." (PMID 39133222, 2024).
laryngeal carcinoma (3 papers, 2017 to 2024). Carcinoma that arises from the laryngeal epithelium. "ALDH1A1 expression has been linked to CSC characteristics and unfavorable clinical outcomes in laryngeal cancer." (PMID 39452555, 2024). "Furthermore, patients with laryngeal cancer had a poorer prognosis when CD44+/ALDH1A1+ cells were present." (PMID 39452555, 2024). "It has been suggested that the co-expression of ALDH1A1 and CD44 is a more precise marker for locating CSCs in laryngeal cancer." (PMID 39452555, 2024). "Several other potential CSC markers have been studied in laryngeal cancer, in addition to CD44 and ALDH1A1." (PMID 39452555, 2024). "Among the most extensively researched CSC markers in laryngeal cancer are CD44 and the aldehyde dehydrogenase 1 family member A1 (ALDH1A1)." (PMID 39452555, 2024).
neuroblastoma (3 papers, 2017 to 2024). Neuroblastoma (NB) is the most common solid, extracranial childhood tumor. "Our findings support a potential interplay between MYCN and c-MYC upon glutamine deprivation, and we initially sought to investigate the co-expression of CSC-related genes such as ALDH1A1 and ALDH1A3 with MYC member expression in the paediatric neuroblastoma patient data from the TARGET study." (PMID 32483461, 2020). "Our data revealed that ALDH1A1 and ALDH1A3 mRNA expression positively correlates with c-MYC gene expression in the neuroblastoma patient samples, and siRNA-mediated c-MYC knockdown inhibited expression of ALDH1A2 and ALDH1A3 genes in the MYCN-amplified neuroblastoma cells." (PMID 32483461, 2020).
papillary thyroid carcinoma (3 papers, 2014 to 2022). "Immunostaining showed that ALDH1A1 positive was expressed in 27 out of 39 (79%) papillary thyroid carcinoma tissues (P=0.0001)." (PMID 31341476, 2019). "ALDH1A1 may, therefore, be used as an indicator of prognosis in patients with papillary thyroid cancer." (PMID 24485040, 2014). "As our results showed, expression levels of ALDH1A1, CD44, OCT3/4, and ABCG2 genes were relevant to papillary thyroid cancer stages starting from stage I to stage III, whereas in the benign tumor it was not." (PMID 31341476, 2019).
prostate adenocarcinoma (3 papers, 2015 to 2023). "ALDH1A1, PTOV1 and CCNG2 transcripts levels are also significantly higher in primary prostatic adenocarcinomas of patients that after radical prostatectomy developed regional or distal metastasis, suggesting their relationship with metastatic progression." (PMID 28938627, 2017).
renal fibrosis (3 papers, 2024 to 2025). A final common manifestation of a wide variety of chronic kidney diseases characterized by glomerulosclerosis and tubulointerstitial fibrosis. "For instance, ALDH1A1 was involved in oxidative stress response and retinoic acid synthesis, both critical in bone remodeling and renal fibrosis." (PMID 41458160, 2025). "Insig1 deletion boosted SREBP1 nuclear localization, increasing Aldh1a1 transcriptional activity, causing excessive NAD+ consumption and ER enlargement, and accelerating renal fibrosis." (PMID 38806641, 2024). "Mechanistically, Insig1 deletion in PTCs boosted SREBP1 nuclear localization, increasing Aldh1a1 transcriptional activity, causing excessive NAD+ consumption and ER enlargement, as well as accelerating renal fibrosis." (PMID 38806641, 2024). "An untargeted metabolomics analysis was carried out to determine the mechanism of Aldh1a1 in renal fibrosis." (PMID 38806641, 2024). "We used PTCs-specific and fibroblast-specific Insig1-knockout mice and whole-body Aldh1a1-knockout mice subjected to UUO or 5/6 nephrectomy (5/6 Nx) to evaluate the importance of PTC-specific Insig1 in conferred protection against renal fibrosis and the maintenance of NAD+ homeostasis." (PMID 38806641, 2024). "However, whether nicardipine affects renal fibrosis or Aldh1a1 deactivation and the related mechanisms are unknown." (PMID 38806641, 2024). "More importantly, we identified nicardipine as a selective inhibitor of Aldh1a1-restored NAD+ and ER homeostasis, which attenuated renal fibrosis." (PMID 38806641, 2024). "We also identified nicardipine as a selective inhibitor of Aldh1a1, which could restore NAD+ and maintain ER homeostasis, as well as improve renal fibrosis." (PMID 38806641, 2024). "Nicardipine treatment was found to be more therapeutically effective than NCT501, and this protective effect was eliminated in Aldh1a1-KO mice, suggesting the involvement of Aldh1a1 in the activity of nicardipine against renal fibrosis, but we could not rule out a potential off-target effect." (PMID 38806641, 2024).
rhabdomyosarcoma (3 papers, 2015 to 2022). A rare aggressive malignant mesenchymal neoplasm arising from skeletal muscle. "This study aimed to evaluate the expression of the selected stem cell markers CD24, CD44, CD133, and ALDH1A1 in rhabdomyosarcoma in children and to determine their prognostic significance in this disease." (PMID 36010245, 2022). "Using our model of gradual selection of rhabdomyosarcoma CSCs, we revealed an apparent upregulation of ALDH6A1 at mRNA and protein level, which was associated with Aldefluor positivity and increased stemness, while ALDH1A1 gene expression was markedly downregulated." (PMID 31941033, 2020).
salivary gland tumors (3 papers, 2016 to 2025). "Hematoxylin and eosin staining revealed a salivary gland tumor with poorly differentiated, solid phenotype with low ALDH1A1 and strong CD44, HLA and keratin-7 expression." (PMID 40371051, 2025). "Strong ALDH1A1 staining was observed in the majority of salivary gland tumors and lung metastases generated by transplantation of ALDHhighCD44high cells." (PMID 40371051, 2025). "Strong expression of ALDH1A1 and minimal CD44 staining was present in salivary gland tumors generated with ALDHhighCD44high cells." (PMID 40371051, 2025).
skin cancer (3 papers, 2016 to 2019). "Recently, a comparative expression analysis of CD44 and ALDH1A1 putative cancer stem cell markers in various skin cancer subtypes was performed." (PMID 27505250, 2016). "Consistently, the expression of Slug was positively correlated with the expression of CSC markers such as CD44, NANOG, ALDH1A1 and KLF4 in skin cancer." (PMID 27901498, 2017).
synovial sarcoma (3 papers, 2013 to 2022). "We have found that SFT and HPC displayed high ALDH1A1 expression at the mRNA level compared to meningiomas and synovial sarcomas." (PMID 24252471, 2013). "ALDH1A1 expression was significantly higher in SFT/HPC as compared with synovial sarcomas (p = 9.4E-08, t-test) with a mean fold change (FC) equal to 9.5." (PMID 24252471, 2013). "We have performed an extensive meningeal SFT/HPC gene profiling study and showed that, at the mRNA level these tumours, and particularly meningeal, had higher ALDH1A1 expression than synovial sarcomas and meningiomas." (PMID 24252471, 2013). "Thus, at the mRNA level, SFT/HPC, and especially the meningeal locations, showed higher ALDH1A1 expression than synovial sarcomas and meningiomas." (PMID 24252471, 2013). "Normalised RNA expression level of ALDH1A1 was available for 52 SFT/HPC, 161 meningiomas and 30 synovial sarcomas." (PMID 24252471, 2013). "ALDH1A1 gene was overexpressed in SFT/HPC, as compared to meningiomas and synovial sarcomas." (PMID 24252471, 2013).
alcohol addiction (2 papers, 2021 to 2022). "Two variations of the ALDH1 enzyme, ALDH1A1*2 and ALDH1A1*3, may be associated with alcohol addiction in Afro-Americans." (PMID 33924016, 2021).
brain cancer (2 papers, 2018 to 2019). A primary or metastatic malignant neoplasm affecting the brain. "Additionally, our studies suggest that the ALDHbright population validates the CSC phenotype based on the increased expression of brain cancer stem cells genes such as ALDH1A1, ITGA6, THY1, PROM1, and SOX2." (PMID 30646520, 2019).
colitis (2 papers, 2013 to 2022). Inflammation of the colon. "In the liver, colitis reduced the mRNA levels of Aldh1a1, Cyp26a1, and Cyp26b1, suggesting reduced production as well as oxidation." (PMID 35889745, 2022). "In the brain, the colitis mice had reduced Aldh1a1 but increased Rarβ mRNA, which might suggest reduced production and perhaps a compensatory induction of the receptor." (PMID 35889745, 2022). "Up-regulated genes in both TNBS-colitis and human IBD included ADA, PrPc, and IL-1α, while down-regulated genes consisted of aldehyde dehydrogenase 1 family, member A1 (ALDH1A1), and PPARγ." (PMID 23382912, 2013). "In adipose tissue, colitis mice had increased Cyp26b1 mRNA levels without increasing the expression of Aldh1a1, suggesting reduced RA concentration." (PMID 35889745, 2022).
congenital heart disease (2 papers, 2021 to 2023). A heart disease that is present at birth. "(iii) For the ALDH1A1 enzyme, there is strong evidence that the A134S and I140T missense mutants are strongly linked to congenital heart disease." (PMID 36450447, 2023).
diabetic retinopathy (2 papers, 2017 to 2023). "On the other hand, ALDH1A1 genes were also found to be expressed principally by Müller glia in diabetic retinopathy." (PMID 37569482, 2023). "In addition we found ALDH1A1, RBP4, APOB, APOA1, RBP1, APOE and RHO genes enriched in retinoid metabolic process as unique GO in diabetic retinopathy." (PMID 28761062, 2017).
Ewing sarcoma (2 papers, 2017 to 2021). A small round cell tumor that lacks morphologic, immunohistochemical, and electron microscopic evidence of neuroectodermal differentiation. "Further, as a transcription factor itself, C/EBPβ regulates the expression of downstream targets, such as ALDH1A1, a potential cancer stem cell marker in Ewing sarcoma and a superior therapeutic target." (PMID 28148901, 2017). "Understanding the molecular contributions of C/EBPβ to ALDH1A1 and other downstream targets in Ewing sarcoma warrants further investigation." (PMID 28148901, 2017). "Because of its role as a cancer stem cell marker and its involvement in transformation and chemoresistance, we directed our focus to understanding ALDH1A1 in Ewing sarcoma and its relationship to C/EBPβ." (PMID 28148901, 2017). "We identified the cancer stem cell marker ALDH1A1 as a target of C/EBPβ in Ewing sarcoma." (PMID 28148901, 2017). "This suggests that C/EBPβ functions as a transcriptional regulator of ALDH1A1 in Ewing sarcoma." (PMID 28148901, 2017). "ALDH1A1 may serve as a biomarker for treatment resistance in Ewing sarcoma patients." (PMID 28148901, 2017).
glaucoma (2 papers, 2011 to 2016). Increased pressure in the eyeball due to obstruction of the outflow of aqueous humor. "Late onset glaucoma in some ARS patients harboring PITX2 mutations may be due to existence of proteins that complement ALDH1A1 activity." (PMID 21617755, 2011). "Effects on ALDH1A1, were further pursued because its protein product, aldehyde dehydrogenase 1 family, member A1, has roles in oxidative stress and because oxidative stress is known to be relevant to the etiology of glaucoma." (PMID 21617755, 2011). "Although the data are preliminary, they are consistent with the proposal that down-regulation of PITX2 causes decreased ALDH1A1 expression, and this may contribute to evolvement of the ARS phenotype, including its glaucoma related features, via oxidative stress related pathways." (PMID 21617755, 2011).
infertile (2 papers, 2010 to 2019). "IPA analysis identified that the oxidation of protein pathway was inhibited due to overexpression of HSPA4 (4.08 folds), ALDH1A1 (10.32 folds) and PARK7 (2.69 folds) proteins in the post-antioxidant treatment group of idiopathic infertile men." (PMID 31623114, 2019).
influenza (2 papers, 2021 to 2023). An acute viral infection of the respiratory tract, occurring in isolated cases, in epidemics, or in pandemics; it is caused by serologically different strains of viruses (influenzaviruses) designated A, B, and C, has a 3-day incubation period, and usually lasts for 3 to 10 days. "The lower expression of Aldh1a1 in the prenatal brain of mice exposed to MIA elicited by influenza, PolyI:C, and interleukin-6 has suggested that this gene is associated with aberrant neural development." (PMID 37851674, 2023).
Insulin resistance (2 papers, 2024 to 2025). Increased resistance towards insulin, that is, diminished effectiveness of insulin in reducing blood glucose levels. "In T2D, reduced ALDH1A1 activity worsens glucose intolerance and insulin resistance." (PMID 40370100, 2025).
lung diseases (2 papers, 2019 to 2021). "Although little is known about the association of ALDH isoforms with lung diseases, ALDH1a1 and ALDH3a1 have been reported to be expressed in the human airway epithelium." (PMID 34425896, 2021).
oropharyngeal cancer (2 papers, 2021 to 2022). Carcinoma, predominantly squamous cell, arising from the epithelial cells of the oropharynx. "Their results showed that HNSCC patients with ALDH1A1 expression displayed a significant p value (p = 0.011) for poor prognosis and those of oropharyngeal cancers with ALDH1A1 expression showed worse prognosis (p = 0.001)." (PMID 34359786, 2021).
oropharyngeal squamous cell carcinoma (2 papers, 2018 to 2024). "Increased ALDH1A1 expression in HNSCC correlates with a low degree of tumor cell differentiation, metastasis to lymph nodes, and duration of a recurrence-free period, which allowed us to propose ALDH1A1 as a prognostic biomarker for oropharyngeal squamous cell carcinoma." (PMID 38540309, 2024). "In addition, the percentage of positive ALDH1A1-expressing cells was significantly increased in lymph node metastases of oropharyngeal squamous cell carcinoma." (PMID 30308036, 2018).
pulmonary fibrosis (2 papers, 2021 to 2023). Chronic progressive interstitial lung disorder characterized by the replacement of the lung tissue by connective tissue, leading to progressive dyspnea, respiratory failure, or right heart failure. "Therefore, we speculated that mesenchymal ALDH1a1 and ALDH4a1 might protect against BLM-induced pulmonary fibrosis." (PMID 34425896, 2021).
rectal adenocarcinoma (2 papers, 2018 to 2026). "We established a human epithelial cell line from a rectal adenocarcinoma overexpressing cancer stem cell marker ALDH1A1, and we investigated the effect of ALDH1A1 knockout on tumor cell traits." (PMID 41631682, 2026).
rectal tumor (2 papers, 2018 to 2020). "There was a trend towards higher levels of ALDH1A1 in right-sided tumors compared to rectal tumors (p = 0.072)." (PMID 30308036, 2018).
schizophrenia (2 papers, 2013 to 2020). A major psychotic disorder characterized by abnormalities in the perception or expression of reality. "For instance, in a 2005 study albumin (ALB) and the RALDH gene ALDH1A1, which oxidises retinaldehyde to at-RA, were significantly downregulated in schizophrenia." (PMID 31666680, 2020). "Seven genes were investigated and involved in the synthesis, degradation and transportation of RA, ALDH1A1, ALDH1A2, ALDH1A3, CYP26A1, CYP26B1, CYP26C1 and Transthyretin (TTR), for their roles in the development of schizophrenia." (PMID 24564241, 2013).
systemic sclerosis (2 papers, 2021 to 2024). A chronic disorder, possibly autoimmune, marked by excessive production of collagen which results in hardening and thickening of body tissues. "A recent study reported that ALDH1A1 is associated with systemic sclerosis and affects the pentose phosphate pathway, oxidative stress and lipolysis, suggesting a relationship between ALDH1A1 and autoimmune diseases." (PMID 38243323, 2024). "Aldehyde dehydrogenase 1 family member A1 (RALDH1)-producing dermal dendritic cells (DCs), a conventional DC subset regulating skin fibrosis, are decreased in the involved skin of patients with systemic sclerosis (SSc)." (PMID 33964960, 2021).